KRAS (KRas proto-oncogene, GTPase)
Diseases named in the same sentence as KRAS in open-access papers (continued):
Sharing a sentence is not in itself a finding about the gene and the disease.
pancreatic cancer (continued). "KRAS activation occurs in more than 70% of pancreatic cancers and the identification of specific inhibitors or combinations that inhibit KRAS signaling has proven to be difficult." (PMID 26018524, 2015). "We therefore used this drug combination as a tool to investigate the resistance mechanism(s) of KRAS mutant cancer cells and the feasibility of targeted therapies for pancreatic cancer." (PMID 26158412, 2015). "Our colleagues have previously demonstrated that other miRNAs (miR-96, miR-217 and miR-27a) function in pancreatic cancer by directly or indirectly affecting KRAS activity, a process that involves PI3K/AKT or RAF-MEK-ERK signaling cascades." (PMID 25905463, 2015). "To further explore the biological function of ATDC in PDA initiation and progression, we generated GEMMs of pancreatic cancer expressing both oncogenic KRAS and ATDC to examine in greater detail the contribution of ATDC to tumor initiation and progression." (PMID 25593307, 2015). "Several theoretically “actionable” aberrations exist in pancreatic cancer including, but not limited to, KRAS, CDKN2A, ARID1A, BRCA, PALB2, PIK3CA, BRAF and so forth." (PMID 25714017, 2015). "Using bioinformatics analysis, we found that miR-217 targeted multiple cancer-related genes that have been reported to have a close link with cancers, such as KRAS (pancreatic cancer), E2F3 (hepatocellular carcinoma), and DACH1 (breast cancer)." (PMID 26016795, 2015). "It is now established that the signals that promote this stromal reaction originate from the KRAS-mutant oncogene in the epithelium of pancreatic cancer cells." (PMID 25935754, 2015). "Recently, preclinical evidence in pancreatic cancer has demonstrated that mutant KRAS can be regulated by EGFR." (PMID 25992771, 2015). "Our results suggest that PTF1A restoration provides an indirect approach to target KRAS-dependency in pancreatic cancer, inhibiting this currently ‘undruggable’, although ubiquitous, cancer-driving mutation." (PMID 26151762, 2015). "Intriguingly, YAP1 is able to functionally compensate for oncogenic KRAS in colorectal and pancreatic cancer mouse models, which is consistent with the fact that RAS mutation and PKN1 mutation are mutually exclusive in the set of ERMS tumors presented here." (PMID 25768946, 2015). "This is one of the major downstream effector pathways of KRAS gene that is being evaluated as a potential target for pancreatic cancer treatment." (PMID 25935754, 2015). "Another study found that (−)-epicatechin specifically inhibited KRAS mutant pancreatic cancer cells in vitro and in vivo." (PMID 26180580, 2015). "The study further suggested that (−)-epicatechin and related compounds can exploit the genetic variations that are intrinsic to cancer cells since KRAS mutant pancreatic cancer cells appear to be particularly sensitive to (−)-epicatechin's anticancer activity." (PMID 26180580, 2015). "Hsa-miR-23a has recently been associated with KRAS and C-MYC mediated signaling pathway, and described as a candidate driving miRNA in pancreatic cancer." (PMID 26121640, 2015). "This is in line with findings that circulating levels of miR-100 are upregulated in the plasma of mutant KRAS-expressing mouse pancreatic cancer models and in patients with pancreatic cancer." (PMID 26132860, 2015). "Computational analyses showed evolutionarily conserved miR-193b binding sites in the 3′-UTR of KRAS, which is known to be an important oncogene in pancreatic cancer." (PMID 25905463, 2015).
pancreatic cancer (continued). "Collectively, these findings suggest that RAGE expression is required for KRAS-mediated activation of HIF1α signaling and pancreatic cancer bioenergetics and growth in vivo." (PMID 25341034, 2014). "Using murine studies as well as molecular, and cellular studies in vitro, we demonstrate here that binding of RAGE to mutant KRAS is a direct, positive regulator of HIF1α-dependent hypoxia signaling in pancreatic tumor development." (PMID 25341034, 2014). "In the first zebrafish model of pancreatic cancer, a mutant KRAS oncogene alone was able to induce pancreatic adenocarcinoma of predominantly acinar or mucinous phenotype." (PMID 24878567, 2014). "Introduction of G4 decoys also resulted in effective inhibition of KRAS and tumor growth arrest in pancreatic cancer cells." (PMID 25071578, 2014). "Knock down of RAGE in vitro inhibits KRAS signaling, promotes HIF1α degradation, and increases hypoxia-induced pancreatic tumor cell death." (PMID 25341034, 2014). "The group also uncovered that EVI1 functioned in proliferation and migration in pancreatic cancer cells and can modulate KRAS protein levels and KRAS-ERK pathway by transcriptionally regulating miR-96 and miR-181." (PMID 25433809, 2014). "Our results provide a novel mechanistic link between NF-κB, KRAS, and HIF1α, three potent molecular pathways in the cellular response to hypoxia during pancreatic tumor development and suggest alternatives for preventive and therapeutic strategies." (PMID 25341034, 2014). "Further studies are required to understand the clinical implication and mechanism of KRAS in pancreatic cancer." (PMID 23425895, 2013). "Analysis revealed that RBM5 expression was negatively correlated with KRAS expression in pancreatic cancer." (PMID 23425895, 2013). "Noteworthy, like most pancreatic cancer cells, MIA PaCa-2 cells harbour a KRAS mutation leading to basal ERK1/2 activation, the latter being essential for MIA PaCa-2 cell proliferation and survival." (PMID 24392017, 2013). "BxPC-3 is a KRAS wild type pancreatic cancer cell line, while the other three cell lines harbor the KRAS mutation." (PMID 24130864, 2013). "Mutations in KRAS and CDKN2A genes in pancreatic cancer are well documented; however, their influence on disease outcome in patients with exocrine pancreatic tumors has remained unclear." (PMID 23565280, 2013). "Since proliferation in pancreatic cancer is driven primarily by KRas, we used siRNA to KRas as a positive control." (PMID 24205284, 2013). "Quantitative RT-PCR and western blot analysis were also performed to detect the expression of KRAS mRNA and protein in 45 pairs of pancreatic cancer vs. peritumoral tissues." (PMID 23425895, 2013). "Our results revealed that the expression of RBM5 and KRAS is negatively correlated in pancreatic cancer." (PMID 23425895, 2013). "This is hardly the case in KRAS downstream pathways, illustrated by the exceedingly low incidence of PIK3CA or BRAF mutations in pancreatic tumors." (PMID 24130864, 2013).
pancreatic cancer (continued). "Only in pancreatic cancer, miR-96 was described to have tumorsuppressive properties by downregulating KRAS thereby impairing cancer cell invasion and migration as well as tumor growth in vivo." (PMID 24260486, 2013). "In a different approach, RNA interference against mutant KRAS has been proven effective in pancreatic cancer cell lines." (PMID 24213498, 2012). "The second stages of pancreatic cancer progression were found to be Small GTPase-dependent signaling and KRAS signaling, which arise independently." (PMID 22069497, 2011). "Inactivation of tumor suppressor gene p16/INK4A and oncogenic activation of KRAS occur in almost all pancreatic cancers." (PMID 22113502, 2011). "In this report, we provided evidence that, while rare in colon and pancreatic cancers, the incidence of KRAS gene amplification (greater than 4-fold) is increased in gastric cancer, and is responsible for KRAS activation." (PMID 19545448, 2009). "First, we show that mutant KRAS dosage gain through allelic imbalance exerts cell-type-specific effects, defining its timing across entities, as exemplified by dosage-sensitive developmental reprogramming during pancreatic cancer initiation." (PMID 41741657, 2026). "Targeting this axis—either by disrupting KRAS signaling or interfering with LD formation and lipid storage—could offer a promising strategy to enhance the efficacy of gemcitabine and other chemotherapeutic agents in KRAS-mutant pancreatic cancers." (PMID 41596564, 2026). "Additionally, exosome-based RNA therapeutics, such as KRAS-targeted siRNA, have shown promise in silencing oncogenes in pancreatic cancer, as demonstrated in Phase I trials." (PMID 40149276, 2025). "Moreover, KRAS alterations drive oncogenesis in the majority of pancreatic cancers (73.40%), while a high proportion of biliary tract tumors (25.35%) presents such alterations." (PMID 40649709, 2025). "Indeed, a recent case report showed objective regression of metastatic pancreatic cancer mediated by TCR-gene therapy targeting KRAS G12D." (PMID 39846249, 2025). "We developed an in vitro stimulation approach and identified HLA-A*11:01–restricted KRAS G12V–reactive CD8+ T cells and HLA-DRB1*15:01–restricted KRAS G12V–reactive CD4+ T cells from peripheral blood of 2 out of 6 HLA-A*11:01–positive patients with pancreatic cancer whose tumors expressed KRAS G12V." (PMID 39846249, 2025). "Notably, it lacks the KRAS mutation and features a homozygous deletion of the SMAD4 gene, making it a valuable resource for studying the genetic landscape of pancreatic cancer." (PMID 40190550, 2025). "Thus, this dual-targeted therapeutic approach holds promise for addressing the challenges posed by KRAS-driven cancers, offering a nuanced and effective strategy to combat pancreatic cancer." (PMID 40382842, 2025).
pancreatic cancer (continued). "Mukhopadhyay Mukhopadhyay S S Undermining Glutaminolysis bolsters chemotherapy while NRF2 promotes chemoresistance in KRAS-driven pancreatic cancers Undermining Glutaminolysis bolsters chemotherapy while NRF2 promotes chemoresistance in KRAS-driven pancreatic cancers Cancer Res." (PMID 40664764, 2025). "Despite these challenges, the discovery of KRAS inhibitors has ushered in a time of cautious optimism that the upward rate of pancreatic cancer deaths and the incremental steps in improvements to the 5-year survival rate of PDAC may soon be in our past." (PMID 40829181, 2025). "Furthermore, T cells engineered to express this TCR specifically recognized all 5 tested human pancreatic cancer organoids that naturally expressed KRAS G12V and HLA-A*11:01, although the recognition was generally modest." (PMID 39846249, 2025). "Since conflicting/opposite impacts of SIRT3 on tumor growth have been reported in the literature, we thus performed patient survival analysis as well as in vitro and in vivo experiments to evaluate the role of SIRT3 on pancreatic cancer development in the context of KRAS activation." (PMID 41391757, 2025). "Currently, the next generation of SLATE targeting only 4 KRAS mutations is being evaluated in combination with nivolumab and ipilimumab in advanced or metastatic NSCLC, microsatellite stable colorectal cancer, pancreatic cancer, and shared neoantigen-positive tumors in a phase 2 study (NCT03953235)." (PMID 41441697, 2025). "To elucidate the mechanism of tumor‐preferential accumulation of DNA origami‐Cy, we hypothesize that macropinocytosis derived by oncogenic KRAS transformation in pancreatic cancer plays a key role in tumor‐selective uptake of DNA origami‐Cy." (PMID 39951277, 2025). "To further evaluate the specificity of TCR-001, we cocultured TCR-001–transduced allogeneic T cells with human pancreatic cancer cell lines naturally expressing KRAS G12 mutations with or without HLA-A*11:01 transfection." (PMID 39846249, 2025). "Notably, the simultaneous inhibition of FTase and GGTase-I has significantly reduced lung and KRAS-driven pancreatic tumors." (PMID 40335986, 2025). "Pancreatic cancer cells, for example, are often found in a hypoxic microenvironment characterised by a specific genetic signature: overexpression and constitutive activation of KRAS, overexpression of NRF2 and HIF-1, and restricted expression of NOS2." (PMID 40567499, 2025). "Notably, the PE corrected the KRAS G13D mutation to its wild-type sequence with editing efficiency of 36.1% in HCT116 human colon cancer cells and 18.7% in ASPC-1 pancreatic cancer cells, while minimizing the occurrence of unintended indel formations." (PMID 40968311, 2025). "A pancreatic cancer cell line displayed differential expression of KRAS and KRASG12D." (PMID 39810420, 2025). "Regarding question 7, both models incorrectly answered that Adagrasib is not indicated for patients with pancreatic cancer harboring the KRAS G12C mutation." (PMID 41049443, 2025). "In pancreatic cancer, inactivation of oncogenic KRAS improves T cell infiltration; furthermore, combination therapy with KRAS inhibitors and immunotherapeutic agents improves responses and delays or prevents acquired resistance to KRAS inhibitors." (PMID 39782689, 2025). "Combining KRAS/ERK inhibitors with standard-of-care chemotherapies could be a promising therapeutic strategy for treating pancreatic cancers." (PMID 41329526, 2025). "Notably, KRAS over-expressing models of pancreatic cancer significantly up-regulate glucose uptake and glycolysis gene expression." (PMID 40950224, 2025). "In this Review, we focus on KRAS as the Achilles’ heel of pancreatic cancer treatment." (PMID 40829181, 2025).
pancreatic cancer (continued). "Here, we demonstrated that combining KRAS inhibitors with gemcitabine effectively overcomes the resistance phenotype associated with CDKN2A loss, highlighting a potential therapeutic strategy for this resistant subset of KRAS-mutant pancreatic cancer." (PMID 40382842, 2025). "Furthermore, TCR-001–transduced CD8+ T cells selectively recognized mutant KRAS G12V 9-mer peptide–pulsed pancreatic cancer cell lines that were transfected to express HLA-A*11:01." (PMID 39846249, 2025). "However, KRAS G12C mutations are rare in PDAC, occurring in less than 2% of cases, thereby limiting the therapeutic relevance of these agents in pancreatic cancer." (PMID 41303394, 2025). "In addition to UCA1, several other lncRNAs have been shown to modulate KRAS downstream signalling in pancreatic cancer." (PMID 40427100, 2025). "The ORGANOPREDICT trial further underscored the predictive power of PDO-based pharmacotyping in advanced refractory pancreas cancer, identifying effective drugs in most cases, even in heavily pretreated individuals, and validating the synergy between KRAS and ERBB inhibitors." (PMID 40829173, 2025). "All pancreatic cancer cell lines, except BXPC3, are characterized by a KRAS mutation." (PMID 40955425, 2025). "This study hypothesizes that the elevated macropinocytic activity in KRAS‐mutant pancreatic cancer cells facilitates the preferential internalization of DNA origami nanostructures, enabling selective targeting, specifically over stroma cells including CAFs." (PMID 39951277, 2025). "It is unknown whether T cells targeting mutant KRAS that are capable of killing tumor cells can be identified from peripheral blood of patients with pancreatic cancer." (PMID 39846249, 2025). "Notably, CaaX‐1 was particularly able to alter Ras‐related signaling pathways in KRas‐mutant pancreatic cancer cells (PANC‐1)." (PMID 40270247, 2025). "When tested in the human gastric cancer AGS cell line and human pancreatic cancer ASPC-1 cell line carrying the KRAS-G12D mutation, the two PROTACs did not exhibit significant advantages over the inhibitor 10k and the positive control drug MRTX1133." (PMID 40430514, 2025). "We further explored the role of KRAS in pancreatic cancer cell survival." (PMID 41322195, 2025). "GATA6 mRNA levels inversely correlated with KRAS/ERK activity in pancreatic tumors." (PMID 41329526, 2025). "However, investigations into 11 pancreatic cancer isogenic cell line pairs revealed that KRAS knockdown induced cell line-specific alterations in DNA methylation, suggesting a role for KRAS in mediating epigenetic regulation." (PMID 40981070, 2025). "Following these promising results, NBF-006 entered a Phase I clinical trial to assess its impact on patients with NSCLC, colorectal, or pancreatic cancer, with or without KRAS mutations." (PMID 40390497, 2025). "Interestingly, these findings mirror those from a pancreatic cancer model in which at 12 weeks after KRAS mutant activation, KrasG12D mice showed more extensive pancreatic intraepithelial neoplasias (PanINs) compared to KrasG12C mice." (PMID 39533328, 2024). "YAP and TAZ promote pancreatic cancer progression, independent of KRAS mutations, and are implicated in metastatic progression." (PMID 39458993, 2024). "In pancreatic cancer, CDC6 interacts with pathways affected by major mutations, like KRAS." (PMID 39052109, 2024).